ADRA2A (adrenoceptor alpha 2A)
Diseases named in the same sentence as ADRA2A in open-access papers (continued):
Sharing a sentence is not in itself a finding about the gene and the disease.
liver fibrosis (1 paper, 2020). "Liver fibrosis is a key factor that contributes to hepatocarcinogenesis; therefore, we detected the expression of ADRA2A in HCC." (PMID 32632241, 2020). "We found that the expression of ADRA2A gradually increased with the development of CCl4-induced liver fibrosis and had a positive correlation with the degree of collagen deposition (R2 = 0.808, P < 0.001)." (PMID 32632241, 2020). "Thus, in this study, we not only utilized an orthotopic HCC implantation mouse model with liver fibrosis to investigate the role of DEX in tumor progression but also explored the correlation between ADRA2A expression and the ECM in mouse liver fibrotic tissues." (PMID 32632241, 2020).
lung carcinoma (1 paper, 2022). "Finally, several genes, such as ADRA2A, P2RY12, ADORA1, CXCR1, and CXCR4, were predicted as potential druggable genes for ALI with GGPPS1-knockout, and were associated with the prognosis of lung cancers." (PMID 35795000, 2022).
lymph node metastasis (1 paper, 2024). "Reduced ADRA2A expression was significantly associated with a high frequency of lymph node metastasis, higher pathological grade, advanced disease stage, and decreased survival among PDAC patients." (PMID 38903083, 2024). "Furthermore, the downregulation of ADRA2A was associated with higher incidence of lymph node metastasis, advanced stages, and high-grade PDAC." (PMID 38903083, 2024).
motion sickness (1 paper, 2021). sympton caused by motion, as sea sickness, train sickness, car sickness, air sickness, or space motion sickness. "To find predictive factors, we investigated the association of ADRA2A rs1800544 and HTR3B rs3758987 with motion sickness susceptibility and examined their mRNA changes during actual voyages." (PMID 34948773, 2021).
pancreatic cancer (1 paper, 2024). "The RNA sequencing data were deposited in the NCBI’s Gene Expression Omnibus (GEO) database under accession number GSE259390: ADRA2A is a suppressor of the basal-like/squamous PDAC subtype and reduces disease aggressiveness of pancreatic cancer." (PMID 38903083, 2024).
sialorrhea (1 paper, 2023). "Two other side effects were reported by the included studies, with Adrenoceptor α 2A (ADRA2A) rs1800544 C/C genotype being linked to sialorrhea." (PMID 36980961, 2023).
thrombophilia (1 paper, 2023). A condition characterized by an abnormally high level of thrombi. "Moreover, we analyze two other clusters: one containing ADRA2A and TBXA2R, the only two thrombophilia-related genes mutated in the healthy subject and the other containing F2, the main antithrombin resistance-causing gene, which is mutated in all subjects." (PMID 37098010, 2023). "ADRA2A and TBXA2R are thrombophilia-related genes mutated in the healthy subject." (PMID 37098010, 2023). "Moreover, the ADRA2A and TBXA2R subnetwork is significantly enriched in“angiogenesis” (GO:0001525), “nervous system development” (GO:0007399) and “vasculogenesis” (GO:0001570) GO Biological Processes, all related to thrombophilia, or vascular disease." (PMID 37098010, 2023).
tumor (10 papers, 2020 to 2026). "Different authors have demonstrated that high expression of ADRA2A was associated with a better prognosis, and its overexpression was capable of suppressing tumor invasion and growth through inhibition of the PI3K/Akt/mTOR pathway." (PMID 36075937, 2022). "ADRA2A encodes a subtype of the adrenergic receptor family and is reported to be expressed in hepatic stellate cells and non-tumor fibrotic liver tissue." (PMID 34070078, 2021). "Immunohistochemistry (IHC) illustrated the presence of ADRA2A protein in the cytoplasm and the cellular membrane of acinar, endocrine, duct, and tumor cells, albeit at lower levels in tumor cells." (PMID 38903083, 2024). "In cancers, ADRA2A exhibits a complex interplay, with reports indicating both tumor-promoting and tumor-suppressing effects across various cancer types." (PMID 38903083, 2024). "This trend indicated that ADRA2A could be an important molecular target that may regulate chemosensitivity in OvCa tumor cells." (PMID 38132444, 2023). "Validation of several of these compounds supports the hypothesis that the activation of ADRA2A may reduce the chemoresistance of OvCa tumor cells and improve the response to CP." (PMID 38132444, 2023). "Evaluation of ADRA2A expression in patient tumors from the TCGA database revealed that ADRA2A is significantly repressed in OvCa tumors, further supporting the hypothesis that inhibition of its signaling may be important in tumor development or progression." (PMID 38132444, 2023). "Thus, taken together, these data further support the idea that the molecular activity of ADRA2A may suppress the resistance of OvCa tumor cells to carboplatin." (PMID 38132444, 2023). "Cancerous squamous cell‐associated genes such KRT5, CDKN2A, and SERPINB3 were mainly enriched in the Stereo‐seq tumor areas, IGKC and IGLC2 were enriched in inflammatory areas, VIM in stromal areas, ADRA2A in blood vessels, and MUC5B in glands." (PMID 35986392, 2022). "Additionally, ADRA2A transcripts displayed downregulation in tumor tissues compared to nontumor tissues in both our NCI-UMD-German cohort and the validation cohort (Moffitt cohort)." (PMID 38903083, 2024). "ADRA2A exhibited a more substantial downregulation in tumor tissues compared to nontumor tissues." (PMID 38903083, 2024).
cancer (7 papers, 2016 to 2024). A tumor composed of atypical neoplastic, often pleomorphic cells that invade other tissues. "ADRA2A has been reported to be expressed in normal fibroblasts but is barely detected in cancer-associated fibroblasts." (PMID 32632241, 2020). "While previous studies have highlighted ADRA2A’s involvement in cancers, its significance in PDAC remains relatively understudied." (PMID 38903083, 2024). "ADRA2A’s impact on critical cancer processes underscores its significance as a potential therapeutic target." (PMID 38903083, 2024). "Elevated ADRA2A induced changes in cancer cell metabolism, resulting in reduced invasion in PDAC cells." (PMID 38903083, 2024). "Understanding the diverse functions of ADRA2A is crucial for elucidating its therapeutic potential in metabolic disorders and cancer treatment." (PMID 38903083, 2024). "In combined treatment with cisplatin, siRNAs against five genes (ADRA2A, F2RL3, NPSR1, NPY and TACR3) enhanced the anti-proliferation efficacy on cancer cells and reduced the self-recovery ability of surviving cells after the removal of the combined treatment." (PMID 36253428, 2022). "Meanwhile, two candidate genes (ADRA2A and DTL) obtained by comparison screening have been reported in cancer." (PMID 34490040, 2021). "Among the remaining 8 DEGs (ADRA2A, P2RX6, XCL2, XCL1, CCL7, TRIM54, TNFRSF18 and SPOCK1), the expression of ADRA2A, the top one, in KIRC based on individual cancer is lower than the normal tissues, but patients with lower expressed ADRA2A have a better overall survival (OS)." (PMID 31159832, 2019). "Three isoforms GP2, RNASE4 and ADRA2A amongst top down-regulated genes are not reported to be differentially expressed in cancer." (PMID 28330331, 2016).
infection (1 paper, 2024). The state of being infected such as from the introduction of a foreign agent such as serum, vaccine, antigenic substance or organism. "Therefore, Lenti CRISPR V2‐gRNA1 was used as an ADRA2A knockout infection plasmid to construct ADRA2A knockout THP‐1 cells, denoted as THP‐1KO." (PMID 38411331, 2024).
ADRA2A also shares sentences with these, for which no sentence is quoted: attention deficit-hyperactivity disorder (3 papers); metabolic syndrome (3); melanoma (2); tauopathy (2); acquired lipodystrophy (1); acute respiratory failure (1); alcohol dependence (1); alcoholism (1); allergic disease (1); Arrhythmia (1); atopic asthma (1); autism (1); bipolar disorder (1); bladder urothelial carcinoma (1); cardiomyopathy (1); Cognitive impairment (1); Coma (1); coronary atherosclerosis (1); coronary diseases (1); deep vein thrombosis (1); delirium (1); dementia (1); endometrial cancer (1); gastritis (1); gastrointestinal disease (1); hyperhomocysteinemia (1); Hyporeflexia (1); hypotension (1); insomnia (1); ischemia (1).
A further 21 diseases each share a sentence with ADRA2A in 1 paper.